ADM (adrenomedullin)
Diseases named in the same sentence as ADM in open-access papers (continued):
Sharing a sentence is not in itself a finding about the gene and the disease.
pneumonia (9 papers, 2009 to 2025). An acute, acute and chronic, or chronic inflammation focally or diffusely affecting the lung parenchyma, caused by an infection in one or both of the lungs (by bacteria, viruses, fungi, or mycoplasma.). "Specifically MR-pro-ADM, is a useful tool for risk stratification of CAP patients, as its levels correlate with indicators linked to the complications of pneumonia, and with outcome." (PMID 29161297, 2017). "Second, bacterial endotoxins and proinflammatory cytokines up-regulate ADM gene expression in many tissues in different forms of infection such as pneumonia." (PMID 19627611, 2009). "In addition, pro-ADM levels were also compared according to the site of pneumonia (unilobar versus multilobar) at admission." (PMID 22818355, 2012). "Among other biomarkers for inflammation, procalcitonin (PCT) had limited added value in the diagnosis of pneumonia in this setting and studies on the prognostic value of the adrenomedullin precursor, mid-regional pro-adrenomedullin (MR-proADM), are currently lacking." (PMID 31747890, 2019). "Recently new attention is being focused on adreno-medullin and specifically on its more stable midregional fragment pro-adrenomedullin (MR-pro-ADM), which has demonstrated to be the most reliable biomarker available in mortality and prognosis prediction for pneumonia (and many other diseases)." (PMID 29161297, 2017).
septic shock (9 papers, 2005 to 2022). Shock caused by infection; frequently caused by gram negative bacteria, although some cases have been caused by other bacteria, viruses, fungi, and protozoa; characterized by fever, chills, tachycardia, tachypnea, and hypotension. "A correlation of plasma ADM in septic shock patients with the relaxation of vascular tone has been previously observed." (PMID 24533868, 2014). "Recently, the more stable mid-regional fragment of pro-adrenomedullin (MR-proADM), comprising amino acids 45–92, which directly reflects levels of the rapidly degraded active peptide ADM, was identified in plasma of patients with septic shock." (PMID 16356231, 2005). "Second, the example of adrenomedullin (ADM)-guided application of adrecizumab in septic shock will demonstrate how biomarkers can guide specific therapies that are part of complex and dynamic clinical syndromes such as septic shock." (PMID 36233650, 2022). "ADM, derived from a larger precursor peptide (pro-ADM), is released into the circulation during systemic inflammation, and the highest plasma concentrations are measured in patients with septic shock." (PMID 26266901, 2014). "We found that serum adrenomedullin when measured at days 0 and 5 of VAP diagnosis may serve as an early predictor of unfavorable outcome (prolonged mechanical ventilation, septic shock, and mortality)." (PMID 36004964, 2022). "Thirteen patients (52.0%) with CRBSI who progressed to a state of septic shock demonstrated significantly increased pro-ADM levels compared with patients without septic shock (5.44 ± 1.17 nmol/L vs 3.54 ± 1.18 nmol/L, P = .001)." (PMID 30334979, 2018). "A non-neutralizing anti-adrenomedullin antibody, Adrecizumab, may improve haemodynamic dysfunction during caecal ligation and puncture-induced septic shock in a murine model." (PMID 31093784, 2019).
asthma (8 papers, 2013 to 2024). "Higher ADM levels are associated with adverse cardiac outcomes and with chronic lung conditions such as asthma or COPD." (PMID 35390066, 2022). "Enhanced expression of adrenomedullin, found in SDNme7−/− lungs, was previously reported in patients with asthma and chronic obstructive pulmonary disease (COPD)." (PMID 33916973, 2021). "The top six upregulated DEG genes (IL6, CXCL8, TNF, DUSP2, ADM, and CXCL1) in SR asthma patients compared with SS asthma patients were identified." (PMID 37208441, 2023). "There was an increased plasma expression of IL-10 and IL-6 in asthma and of c-x-c motif chemokine ligand 2 (CXCL2) and adrenomedullin (ADM) in pulmonary TB." (PMID 33023021, 2020). "Examples found here to be up-regulated in CF include ADM (adrenomedullin), a vasodilator which promotes alveolar development and repair, and which is speculated to have a protective effect in the immuno-inflammatory process of asthma, implying that it may respond to airway injury in CF." (PMID 23537407, 2013).
colorectal cancer (8 papers, 2013 to 2025). A primary or metastatic malignant neoplasm that affects the colon or rectum. "In colorectal cancer studies, ADM expression has been positively correlated with MMP-9 expression, and their combined activity has been shown to enhance the migration and invasion of colorectal cancer cells." (PMID 40565016, 2025). "We then selected the 4 colorectal cancer-related genes ADM, DKK1, HAS3 and SMURF2 for quantitative real-time PCR verification." (PMID 23922913, 2013). "Similarly, in colorectal cancer, ADM is among the most selectively upregulated genes in KRAS-mutant cells under hypoxia, and its expression is markedly reduced upon KRAS silencing, highlighting ADM as a key downstream effector of KRAS-driven tumorigenesis in hypoxic niches." (PMID 40547013, 2025).
renal dysfunction (8 papers, 2021 to 2025). "Our findings are, however, consistent with an association of renal dysfunction and disease severity with plasma ADM levels reported previously." (PMID 40447978, 2025). "In conclusion, coagulation abnormalities, liver dysfunction, renal dysfunction, and raised levels of adrenomedullin and procalcitonin were associated with worse outcomes." (PMID 41013386, 2025). "Mortality was significantly associated with deranged coagulation parameters (INR, aPTT), liver dysfunction (elevated AST), renal dysfunction (elevated creatinine), and higher levels of adrenomedullin and procalcitonin." (PMID 41013386, 2025). "Other biomarkers evaluated as predictors of adverse outcome are galectin-3, growth differentiation factor 15, mid-regional pro-adrenomedullin, and makers of renal dysfunction." (PMID 33852110, 2022). "In this study, we investigated the plasma clearance of synthetic human adrenomedullin (AM) in two models of rats with renal dysfunction; one was induced by subcutaneous injection of mercury chloride (RD-Ag) and the other by completely blocking bilateral renal blood flow (RD-Bl)." (PMID 36139120, 2022). "Moreover, pro-ADM and copeptin correlated with both NT-pro-BNP and creatinine, suggesting a relation with acute, IE-associated cardiac dysfunction, and also a strong influence of renal dysfunction on biomarker levels." (PMID 33413127, 2021).
type 2 diabetes (8 papers, 2010 to 2022). "Here, we investigated whether ET-1 and ADM, measured as C-terminal-proET-1 (CT-proET-1) and mid-regional-proADM (MR-proADM), respectively, were associated with incident type 2 diabetes." (PMID 35681200, 2022). "Adrenomedullin is involved in insulin regulatory system and is elevated in plasma from patients with pancreatic dysfunctions such as type 1 or type 2 diabetes and insulinoma." (PMID 20181139, 2010). "Adrenomedullin might play a role in the pathogenesis of diabetic vasculopathy in type 1 and type 2 diabetes." (PMID 20181139, 2010). "In humans, plasma ADM concentrations are elevated in obese individuals and patients with T2DM type 2 diabetes." (PMID 35324977, 2022).
coronary artery disease (7 papers, 2014 to 2022). "Adrenomedullin is a biomarker for coronary artery disease and HF, but little is known about the peptide in AF." (PMID 36430541, 2022). "Chronic ischemia can also downregulate epicardial fat adrenomedullin secretion in advanced stages of coronary artery disease, although cytokines levels are likely regulated by a complexity of hemodynamic factors." (PMID 35822028, 2021). "The expression of these cardioprotective adipokines, such as adiponectin and adrenomedullin, is reduced in advanced coronary artery disease." (PMID 35822028, 2021). "Thus, based on our current findings it could be tempting to hypothesize that MR-pro-ADM acts as a link between coronary artery disease and low-energy-fractures among men." (PMID 30216373, 2018).
lung carcinoma (7 papers, 2016 to 2025). "Among the patients with lung cancer, serum ADM concentration is associated with the incidence of the abnormal T wave." (PMID 35355972, 2022). "Overall, our results demonstrated that patients with lung cancer with higher ADM levels have a tendency to increase the risk of myocardial ischemia compared to lung cancer patients with lower ADM levels." (PMID 35355972, 2022). "To experimentally validate these findings, we performed RT-qPCR analysis following ADM knockdown in lung cancer cells." (PMID 40547013, 2025). "By evaluating the relationship between adrenomedullin (ADM) and myocardial ischemic T wave changes, the clinical value of circulating ADM as a predictor of myocardial ischemia in patients with lung cancer is confirmed." (PMID 35355972, 2022). "Among 427 genes reported in the first study as being differentially expressed in subjects with lung cancer are included 11 of our smoking-related DEGs and 18 DMGs, including hub genes ADM and SMAD3." (PMID 26837704, 2016). "Elevated serum ADM levels in patients with lung cancer are correlated with increased incidence of the negative or flat T wave, which has been implicated in chronic myocardial ischemia." (PMID 35355972, 2022). "A previous study has investigated the prognostic role of ADM in lung cancer; however, it was found that ADM expression was not correlated with the survival of patients with lung cancer." (PMID 33340396, 2020).
Stroke (7 papers, 2017 to 2025). Sudden impairment of blood flow to a part of the brain due to occlusion or rupture of an artery to the brain. "In fact, patients with stroke disclosed ADM overexpression and higher ADM expression correlates with stroke severity and poor prognosis." (PMID 40387073, 2025). "Cardiovascular function pathways regulated at 5-h post-stroke that correlated with 90d outcomes included Adrenomedullin signaling pathway, Renin–Angiotensin Signaling and HIF1α Signaling." (PMID 36691064, 2023). "We evaluated the potential value of 4 key hub genes (ADM, PTGS2, VCAN, and MMP9) in stroke diagnosis." (PMID 39519172, 2024). "However, there are no studies utilizing adrenomedullin over-expression in stroke or another brain ischemia/hypoxia model." (PMID 28620317, 2017).
breast tumour (6 papers, 2003 to 2026). "Breast tumor cells secreted ADM that modified cancer–associated adipocytes through paracrine signaling, leading to metabolic changes and delipidation." (PMID 32819314, 2020). "In addition, breast tumour cell-secreted adrenomedullin has been shown to modify cancer-associated adipocytes through paracrine signalling, leading to metabolic changes and lipolysis." (PMID 38301482, 2024). "Breast tumours secrete a variety of factors that modify the phenotype and function of adjacent adipocytes, among which adrenomedullin (ADM) has been identified as a key mediator." (PMID 41498391, 2026). "Note that in breast tumors, lipolysis can be accompanied by browning of adipocytes adjacent to the tumor tissue through adrenomedullin (ADM) secretion." (PMID 33466493, 2021). "For instance, ADM expression is enhanced in the serum of patients with high-grade breast tumors and is correlated with lymph node metastasis." (PMID 33466493, 2021). "Breast tumor mammospheres secreted ADM, which is known to be highly produced in hypoxic environments of several tissues, including adipose tissue." (PMID 32819314, 2020). "In the present work, we have examined ADM peptide expression in a series of malignant breast tumours by immunohistochemistry using a newly developed anti-ADM monoclonal antibody." (PMID 14612905, 2003). "The series of breast tumours that we have examined shows that ADM is expressed in the majority of the carcinomas." (PMID 14612905, 2003). "ADM-peptide expression in breast tumours was significantly correlated with axillary lymph node metastasis (P=0.030)." (PMID 14612905, 2003).
colitis (6 papers, 2013 to 2017). Inflammation of the colon. "We previously reported that a traditional Japanese medicine, daikenchuto (TU-100), ameliorated a trinitrobenzenesulfonic acid- (TNBS-) induced type-1 model colitis exhibiting histopathological features of CD through adrenomedullin (ADM) enhancement." (PMID 24348533, 2013). "Considering that the effect of TU-100 is related to endogenous ADM in the intestines, we hypothesized that TU-100 would be effective in treatment of other types of colitis with different immunological properties." (PMID 24348533, 2013). "Induction of adrenomedullin and CGRPs by the ginger shogaols and Japanese pepper sanshools appear to play a role since neutralization of adrenomedullin decreases the anti-inflammatory effects of TU-100 in TNBS colitis." (PMID 24857966, 2014).
depression (6 papers, 2016 to 2023). "In this study, we examined the effects of two Yin yoga-based interventions on the vasoactive peptide adrenomedullin (ADM) and common psychological risk factors of NCDs, including stress, anxiety, depression, and insomnia." (PMID 30020987, 2018). "Another interaction was between UT-Other and a SNP upstream of the SBF2/ADM genes; SBF2 was associated with addiction, and ADM was associated with anxiety, depression and bipolar disease." (PMID 28002425, 2016). "ADM, which acts as a vascular inhibitor, is upregulated in major depressive disorder, suggesting that ADM may be associated with neuroinflammation-related diseases." (PMID 38102696, 2023). "The neuropeptides adrenomedullin, insulin-like growth factor 2, prodynorphin, and resistin were identified as mutually expressed in both periodontitis and depression, also playing a role in identifying depression." (PMID 37396968, 2023). "Elevated ADM was found in patients with major depression, and according to a large population-based study, plasma ADM partly explains the relationship between depressive symptoms and mortality risk during long-term follow-ups." (PMID 30020987, 2018). "In support of this, we found significant relationships between changes in ADM and changes in depression, which replicates the findings of previous research." (PMID 30020987, 2018). "Besides, in two case-control studies of blood microarrays in major depressive disorder, a total of 165 genes were differentially expressed in both studies with the concordant direction of fold change, with the ADM gene also present in our DEGs." (PMID 34667146, 2021).
periodontitis (6 papers, 2016 to 2024). An acute or chronic inflammatory process that affects the tissues that surround and support the teeth. "The inactivation of the ADM signaling pathway was predicted in T2DM-related periodontitis." (PMID 38241313, 2024). "In contrast, the Superpathway of Cholesterol Biosynthesis, Adrenomedullin (ADM), and Superpathway of Inositol Phosphate Compounds (SIPC) were inhibited in tissues with periodontitis in the diabetic patients." (PMID 38241313, 2024). "The IPA also predicted the inhibition of Cholesterol Biosynthesis, Adrenomedullin, and Inositol Phosphate Compounds pathways in T2DM-related periodontitis." (PMID 38241313, 2024). "The neuropeptide genes ADM, IGF2, PDYN, and RETN were intersected between periodontitis and MDD, and FOSB was a crosstalk gene related to these neuropeptides on the transcriptomic level." (PMID 34721734, 2021). "In the Pg sample, we observed interactions between ADM and CALCRL, which is related to periodontitis; EDA and EDA2R, which is related to ectodermal development; and SPP1 and CD44 and SPP1 and (ITGA4+ITGB1), which promotes phosphoprotein secretion and regulates bone salinization." (PMID 37287452, 2023). "Similarly, systemic markers of atherosclerosis: adrenomedullin and chemokine (C-C motif) ligand 28 levels changed significantly in the periodontitis and atherosclerotic patients, compared to the non-artherosclerotic periodontitis patients following non-surgical periodontal treatment." (PMID 28959211, 2017).
preeclampsia (6 papers, 2020 to 2024). Preeclampsia is a hypertensive disorder of pregnancy that is characterized by new-onset hypertension with proteinuria presenting after 20 weeks of gestation, and depending on mild or severe forms may initially present with severe headache, visual disturbances, and hyperreflexia. "Circulating ADM mRNA levels are decreased at 28 and 36 weeks’ gestation in women developing preeclampsia compared with controls." (PMID 36180668, 2023). "The vasoactive peptide adrenomedullin (ADM) is a potent vasodilator with implications in both preeclampsia and cardiovascular disease." (PMID 34362171, 2021). "One study observed that levels of mid-regional pro-ADM were low in patients with serious preeclampsia." (PMID 32025333, 2020). "In the sera of patients who developed gestational hypertension later in pregnancy, higher concentrations of both MR-proANP (GH, 880 ± 110 pg/mL vs. non-GH, 390 ± 30 pg/mL; p < 0.001) and adrenomedullin (GH, 295 ± 74 pg/mL vs. non-GH, 100 ± 4.5 pg/mL; p < 0.001) were found." (PMID 39682578, 2024).
acute myeloid leukemia (5 papers, 2021 to 2025). Acute myeloid leukemia (AML) is a group of neoplasms arising from precursor cells committed to the myeloid cell-line differentiation. "In the context of acute myeloid leukemia, the expression of ADM is linked to stem cell phenotypes, inflammatory attributes, and genes associated with immune suppression." (PMID 38256104, 2024). "Additionally, the ADM‐CRLR axis regulates drug‐tolerant, relapse‐initiating cells in acute myeloid leukaemia." (PMID 40074697, 2025).
acute respiratory distress syndrome (5 papers, 2023 to 2025). Progressive and life-threatening pulmonary distress in the absence of an underlying pulmonary condition, usually following major trauma or surgery. "Several studies have demonstrated that combining adrenomedullin (ADM) with other biomarkers significantly enhances the sensitivity for diagnosing acute respiratory distress syndrome (ARDS) in septic patients." (PMID 39594987, 2024). "In an LPS-induced acute respiratory distress syndrome (ARDS) mouse model, RAMP2 and RAMP3 were found to play crucial roles inflammatory modulation functions of ADM." (PMID 40565016, 2025).
chronic heart failure (5 papers, 2021 to 2024). "The increase in blood volume and activation of sympathetic nerves in patients with chronic heart failure leads to an increase in plasma ADM concentration." (PMID 35116032, 2021). "Adrenomedullin (ADM) is a vasodilatory peptide expressed in different tissues with potent hypotensive effects, and its levels are known to be elevated in patients with chronic heart failure." (PMID 38248885, 2024).
gastric cancer (5 papers, 2017 to 2025). A primary or metastatic malignant neoplasm involving the stomach. "We used siRNA gene silencing, in BGC-823 gastric cancer cell lines, to target adrenomedullin genes, and found that increased adrenomedullin expression results in the proliferation of tumor cells, tumor invasion, and metastasis." (PMID 29179449, 2017). "In this study, we examined the role of adrenomedullin in the pathogenesis of gastric cancer." (PMID 29179449, 2017). "Adrenomedullin has been shown to be overexpressed in many tumors, including gastric cancer tumors; however, its mechanism of action remains unclear." (PMID 29179449, 2017). "Furthermore, we found that under hypoxic conditions, gastric cancer BGC-823 cells exhibit higher expression levels of adrenomedullin and various other related proteins." (PMID 29179449, 2017). "Therefore, the knockdown of adrenomedullin and its receptors may represent a novel treatment strategy for gastric cancer." (PMID 29179449, 2017). "Similar to our results, a gastric cancer study found that neither G-CSF, GM-CSF, TGF-β, M-CSF, IL-1β, IL17A, IL-6, TNFα, IL10, IFNγ and IL22 were able to induce MC degranulation, while only adrenomedullin did." (PMID 32722549, 2020).